MEIS2 (Meis homeobox 2)
Diseases named in the same sentence as MEIS2 in open-access papers (continued):
Sharing a sentence is not in itself a finding about the gene and the disease.
ovarian carcinoma (8 papers, 2011 to 2025). A malignant neoplasm originating from the surface ovarian epithelium. "Conversely, high expression of MEIS2 is associated with improved prognosis in ovarian cancer patients." (PMID 39776641, 2024). "In ovarian cancer, high MEIS2 protein expression has been associated with improved prognosis whereas high RNA expression of MEIS2 has been associated with worse overall survival in colorectal cancer." (PMID 31640805, 2019). "Regarding MEIS2 expression, this gene has been found in immature neuronal precursor cells, lens proliferative cells, ovarian cancer, and other tumor cell types, which underlies its possible role in sustaining proliferation." (PMID 22185299, 2011). "However, it has been also shown that high expression of MEIS2 is associated with improved prognosis of ovarian cancer." (PMID 37621680, 2023). "Furthermore, studies have found that Meis2 holds carcinogenic effects in the development of neuroblastoma, leukemia, bladder cancer, prostate cancer, and ovarian cancer." (PMID 35416122, 2022). "For example, Meis2 has been revealed to be overexpressed in ovarian cancer and inhibit the proliferation and tumorigenicity of ovarian cancer cells, which was connected to improving the prognosis for patient with ovarian cancer." (PMID 35416122, 2022). "MEIS2 is widely expressed in ovarian cancer and markedly affects its occurrence." (PMID 33975520, 2021). "For examples, MEIS2 functions as an oncogene in AML and ovarian cancer." (PMID 38711262, 2024).
breast carcinoma (7 papers, 2018 to 2024). "The expression level of MEIS2 is associated with breast cancer clinical stages and pathological grades, suggesting its potential value for breast cancer prognostics." (PMID 38711262, 2024). "We revealed the underlying mechanism by which MEIS2 affected breast cancer cell growth and tumor development." (PMID 38711262, 2024). "Gene expression analysis has shown that MEIS2 expression is associated with the proliferation of breast cancer (BC) cells, but the role of MEIS2 in BC and its underlying mechanism remain elusive." (PMID 38711262, 2024). "Furthermore, the suppressive role of MEIS2 in breast cancer cell proliferation is associated with the IL10 expression and myeloid cells infiltration." (PMID 38711262, 2024). "The underlying mechanism may be that MEIS2 affected breast cancer cell proliferation, migration, as well as the infiltration of myeloid cells in BC by regulating the IL10 expression." (PMID 38711262, 2024). "In sum, our study revealed that the homeobox protein MEIS2 acts as a tumor suppressor in the development of breast cancer (ER− and ER+)." (PMID 38711262, 2024). "Using human BC cell lines, clinical samples and animal xenograft model, we reveal that MEIS2 functions as a tumor suppressor in breast cancer." (PMID 38711262, 2024). "Our study demonstrates that the tumor suppressor of MEIS2 in breast cancer progression is partially via down regulating the expression of IL10 and promoting myeloid cells infiltration." (PMID 38711262, 2024). "MEIS2 knockdown (MEIS2‐KD) promotes while MEIS2 overexpression suppresses breast cancer cell proliferation and tumor development in vitro and in animal xenograft models, respectively." (PMID 38711262, 2024). "Here, we demonstrate that MEIS2 acts as a suppressor in breast cancer (ER− and ER+), which is partially due to the MEIS2‐IL10 signaling." (PMID 38711262, 2024). "MEIS2 mediates breast cancer cell growth and the infiltration of myeloid cells by regulating IL10 expression." (PMID 38711262, 2024). "And MEIS2 silence enhanced the ability of mobility and colony formation in breast cancer cells." (PMID 38711262, 2024). "We found the amount of MEIS2 knock‐down breast cancer cells is much more than the control group after 5 days, indicating that knockdown of MEIS2 significantly increased the proliferation rates of both MDA‐MB‐231 and T47D MEIS2‐KD cells as compared with their control cells." (PMID 38711262, 2024). "Results from a transcriptomic array indicated a series of newly described transcription factors including HOXB7, MEIS2, TCERG1, and DNAJC2, that were associated to poor outcome in HER2+ breast cancer subtype and downregulated by the MZ1-trastuzumab combination." (PMID 33741018, 2021). "However, the role of MEIS2 in the development of breast cancer is still unclear." (PMID 38711262, 2024). "Investigation of MEIS2 in low-grade prostate tumors suggested that it plays a critical function related to poor prognosis and might be a useful biomarker or therapeutic target in breast cancer." (PMID 29757984, 2018). "Results show that the knockdown of MEIS2 in breast cancer cells up‐regulates the IL10 expression, but MEIS2 overexpression opposed the effect on IL10 expression." (PMID 38711262, 2024). "Furthermore, our studies suggest that MEIS2 downregulates the expression of IL10 to suppress breast cancer growth, and MEIS2‐IL10 signaling is partially associated with MDSCs infiltration in BC." (PMID 38711262, 2024). "MEIS2, which belongs to the same family of HOXB7, has been also reported to be a master regulator in breast cancer." (PMID 33741018, 2021). "Additionally, MEIS2‐mediated IL10 contributes to breast cancer cell growth, knockdown IL10 significantly reduced the proliferation rate of MEIS2‐KD breast cancer cells." (PMID 38711262, 2024).
breast carcinoma (continued). "The real‐time PCR analysis showed that the expression level of IL10 is highly upregulated in MEIS2 knockdown cancer cells, while significantly decreased in MEIS2 overexpressed cells, indicating that MEIS2 can affect the IL10 expression level in breast cancer cell." (PMID 38711262, 2024).
cleft palate (7 papers, 2015 to 2024). Cleft palate is a fissure type embryopathy that affects the soft and hard palate to varying degrees. "MEIS2 is linked to cleft palate, cardiac defects, and impaired intellectual development (CPCMR, MIM# 600987), whereas NUSAP1 has been described as tolerant of loss-of-function." (PMID 39639090, 2024). "Another individual with syndromic cleft palate (Family 10) harbored an inversion disrupting MEIS2 (MIM: 601740), a gene linked to cleft palate, cardiac defects, and impaired intellectual development (MIM: 600987)." (PMID 38776926, 2024). "Pathogenic variants in MEIS2 are associated with a syndrome known as “cleft palate, cardiac defects, and impaired intellectual development” (CPCMR, MIM# 600987)." (PMID 39639090, 2024). "Molecular and genomic analyses revealed that MEIS2 directly regulates important osteogenic genes, and specific inactivation of the MEIS2 gene in cranial neural crest cells resulted in complete cleft palate or submucous cleft and complete loss of palatal bone." (PMID 39776641, 2024). "Heterozygous loss of MEIS2 (MIM# 600987) is associated with a cleft palate, heart malformations, and intellectual impairment, which overlap with the clinical symptoms observed in the proband." (PMID 39639090, 2024). "Recently, several patients with congenital craniofacial malformations such as cleft palate have been described as carrying heterozygous mutations in MEIS2 gene." (PMID 32616504, 2020). "According to some authors, the MEIS2 gene should be considered among the candidate causative genes in cases without 22q11.2 deletions in patients with cleft palate." (PMID 32616504, 2020).
colorectal cancer (6 papers, 2019 to 2026). A primary or metastatic malignant neoplasm that affects the colon or rectum. "Homeobox protein MEIS2 has been strongly implicated in colorectal cancer (CRC) progression and metastatic potential, making its targeted inhibition a promising therapeutic strategy." (PMID 42073401, 2026). "Distant metastasis and associated mortality are closely related to Meis2 expression in colorectal cancer." (PMID 33402862, 2020). "In colorectal cancer, MEIS2 promotes cell migration and invasion." (PMID 36835058, 2023). "MEIS1 could trigger cell proliferation in colorectal cancer, while MEIS2 determines the relationship between colorectal cancer growth and death." (PMID 33402862, 2020). "In vitro and in vivo studies have suggested that MEIS2 may inhibit migration, invasion, and the epithelial to mesenchymal transition of colorectal cancer." (PMID 33402862, 2020). "Thus, MEIS2 knockdown increases responsiveness to chemotherapy in multiple myeloma, whereas MEIS2 is downregulated in colorectal cancer patients resistant towards oxaliplatin-based chemotherapy." (PMID 31640805, 2019). "Moreover, high Meis2 expression may reduce the overall survival period of patients with colorectal cancer." (PMID 33402862, 2020). "Although epigenetic silencing of MEIS2 has also been described in lung and hepatocellular carcinoma cell lines as well as colorectal cancer, the function of MEIS2 in other cancers remains unclear and may be highly disease-specific as MEIS2 is downregulated in some cancers and upregulated in others." (PMID 31640805, 2019). "The expression levels of VSIG4, ZNF532, MEIS2, and CXCL13 were downregulated, while CXCL10 was elevated between colorectal cancer and normal tissues." (PMID 36909170, 2023).
leukemia (6 papers, 2011 to 2024). A malignant (clonal) hematologic disorder, involving hematopoietic stem cells and characterized by the presence of primitive or atypical myeloid or lymphoid cells in the bone marrow and the blood. "Together, these data suggest that MN1 leukemia is associated with substantial upregulation of Meis2 and this upregulation may play a key role in MN1 leukemia." (PMID 28960191, 2017). "Together, these data provide new evidence that Meis2 contributes to the block in in vitro apoptosis characteristically seen in MN1 leukemia." (PMID 28960191, 2017). "However, in acute myeloid leukemia (AML)‐ETO‐positive leukemia, in which MEIS2 is up‐regulated, MEIS2 plays an oncogenic role through impairing repressive DNA binding of AML1‐ETO, resulting in upregulation of proto‐oncogenes such as YES1 kinase in AML cells." (PMID 38711262, 2024). "MEIS2 plays a role in acute myeloid leukemia (AML)-ETO-positive leukemia." (PMID 39776641, 2024). "However, we identified Meis2 as critical to MN1-induced leukemia, with essential roles in proliferation, self-renewal, impairment of differentiation and disease progression in vitro and in vivo." (PMID 28960191, 2017). "Furthermore, knockdown of Meis2 in our leukemia-derived MN1 cell line results in an approximately 10-fold increase in Meis1 expression (unpaired t-test, n.s.), supporting compensatory expression between these family members." (PMID 28960191, 2017). "To test the effect of Meis2 knockdown on MN1 leukemia, we used two different murine models." (PMID 28960191, 2017). "Most notable among these is Meis2, which we find to be strikingly upregulated in MN1 leukemic cells and essential for MN1 leukemogenic activity in the murine leukemia model." (PMID 28960191, 2017). "Here we show increased expression of MEIS1, MEIS2, and PREP1 genes in leukemia-derived cell lines compared with blood normal cells." (PMID 22185299, 2011). "In that we observed dissimilar MEIS1, MEIS2, and PREP1 expression levels, we wished to confirm whether these changes were also observed in samples of patients with leukemia." (PMID 22185299, 2011). "Knockdown of Meis2 significantly increases the latency of disease in both MN1 leukemic models, with median latency of disease onset increasing from 41 to 50 days in the leukemia-derived MN1 model (Mantel–Cox, P=0.001) and from 47 to 55 days in the primary MN1 cell line model (Mantel–Cox, P=0.0119)." (PMID 28960191, 2017).
developmental delay (4 papers, 2020 to 2025). "We report a case of de novo heterozygous frameshift mutation in the MEIS2 gene that resulted in developmental delays and a phenotypic overlap of cardiac, craniofacial, and other abnormalities." (PMID 39776641, 2024). "The two siblings of this study only present mild developmental delay and bifid uvula, while patient A and patient H didn’t show palate defects, which occur in 80% (16/20) of MEIS2 mutations, and 85% (22/26) of other microdeletion and duplication cases." (PMID 34930369, 2021). "Taken all together, this study has important implications for genetic counseling regarding recurrence risk and also points to the importance of offering MEIS2 gene tests covering both point mutations and microdeletions to individuals with milder bifid uvula and developmental delay." (PMID 34930369, 2021). "It was also identified as a risk factor in an open-angle glaucoma GWAS, and MEIS2 missense mutations and microdeletions have been found in patients with ASD and developmental delay." (PMID 32393163, 2020). "Here, we present one family with a 423 kb deletion encompassing the last three exons of the MEIS2 (15q14) gene in two siblings with bifid uvula and mild developmental delay and the same deletion as a mosaic lesion in the father with a congenital atrial septal defect." (PMID 34930369, 2021). "10, 11, and 12) of the MEIS2 gene (NM_170676.5) and CDIN1 in two siblings, presenting mild developmental delay and bifid uvula." (PMID 34930369, 2021).
multiple myeloma (3 papers, 2019 to 2023). "Our study provides evidence on the role of MEIS2 in MM cell survival and suggests therapeutic strategies targeting of MEIS2 to enhance IMiDs anti-myeloma activity." (PMID 30975979, 2019). "Emerging evidence suggests that IMiDs can block MEIS2 from binding to CRBN facilitating the subsequent activation of a CRL4CRBNIMiD-E3-ubiquitin ligase activity and proteasome-mediated degradation of critical substrates regulators of Multiple Myeloma (MM) cell survival and proliferation." (PMID 30975979, 2019).
prostate tumors (3 papers, 2013 to 2020). "On the other hand, our prior studies show that prostate tumors frequently harbor downregulation of the transcription factors and HOX binding partners MEIS1 and MEIS2 (myeloid ecotropic viral integration site 1/2)." (PMID 32553107, 2020). "The role of MEIS2 and MEIS1 in low-grade prostate tumors suggests that they play a critical function in the formation of poor prognosis." (PMID 24391925, 2013).
thyroid cancer (3 papers, 2020 to 2024). "Based on this, we used a human papillary TC cell line as a study target to investigate its effects and mechanisms on proliferation and apoptosis of thyroid cancer cells by interfering with the expression of MEIS2." (PMID 33975520, 2021). "Investigation of effects of Meis homeobox 2 (MEIS2) on proliferation and apoptosis of thyroid cancer (TC) cells and its specific molecular mechanism is the main purpose of this study." (PMID 33975520, 2021).
ventricular septal heart defects (3 papers, 2021 to 2024). "Humans carrying heterozygous MEIS2 missense mutations or 15q14 microdeletion involving MEIS2 present a triad of cleft palate, atrial or ventricular septal heart defects, and developmental delay." (PMID 36418415, 2022).
anemia (2 papers, 2015 to 2018). A reduction in the number of red blood cells, the amount of hemoglobin, and/or the volume of packed red blood cells. "Meis2 knockout mice display smaller livers and severe anemia, suggesting that Meis2 may play a role in mouse embryonic hematopoiesis." (PMID 30526668, 2018). "Having observed anemia in Meis2-/- embryos we further pursued the possibility that Meis2 may influence embryonic hematopoiesis similarly to Meis1 that controls proliferation of hematopoietic stem cells in the fetal liver and is also essential for megakaryocyte viability." (PMID 26545946, 2015).
glioma (2 papers, 2020 to 2022). A benign or malignant brain and spinal cord tumor that arises from glial cells (astrocytes, oligodendrocytes, ependymal cells). "In glioma, Meis1 expression is high, while Meis2 expression is low." (PMID 33402862, 2020). "Gene expression analysis of glioma and glioblastoma cells revealed that Meis2 was one of the differentially expressed genes and it could be a prognostic biomarker for glioma and glioblastoma development, in addition to with other genes, including Meox2, Pitx2, Nr2e1, and Tfap2B." (PMID 33402862, 2020).
hepatocellular carcinoma (2 papers, 2019). A malignant tumor that arises from hepatocytes. "Our study aims to identify the regulatory mechanisms of MEIS2 in hepatocellular carcinoma (HCC), which could be targeted to develop new therapeutic strategies." (PMID 31623651, 2019).
learning disability (2 papers, 2017 to 2021). A group of disorders that affect a person's ability to learn or process specific types of information which is in contrast to his/her apparent level of intellect. "Loss of MEIS2 has been shown to cause delayed motor development and learning disability, suggesting m6A regulation may be an important mechanism to guard against AD phenotypes." (PMID 33402207, 2021). "Similar phenotypic features (asymmetry of the thorax, bifid uvula, and a specific learning disability) were found in one patient with MEIS2 deletion reported in the DECIPHER database." (PMID 28934986, 2017).
liver cancer (2 papers, 2019 to 2024). An epithelial or non-epithelial malignant neoplasm that arises from the liver. "High levels of MEIS2 are correlated with poor survival rates in patients with liver cancer." (PMID 39776641, 2024). "To determine whether MEIS2 has important roles in liver cancer, we compared the expression of MEIS2 mRNA and protein in a cohort of 118 human HCCs and their paired adjacent noncancerous liver (ANL) samples." (PMID 31623651, 2019).
myocardial infarction (2 papers, 2022 to 2024). Gross necrosis of the myocardium, as a result of interruption of the blood supply to the area, as in coronary thrombosis. "Knockout of RB1 and Meis2 in adult cardiomyocytes induced cell cycle reentry and improved function of cardiac repair after myocardial infarction." (PMID 37642904, 2024). "Knockout of Rb and Meis2 may lead to cell cycle re‐entry of adult cardiomyocytes and promote heart repair after myocardial infarction." (PMID 36278684, 2022).
pancreatic cancer (2 papers, 2011 to 2023). "The nearest gene (located at a distance of about 500 kb) is myeloid ecotropic insertion site homeobox 2 (MEIS2), which is known to be expressed at high levels in the pancreas and in pancreatic cancer (data from the In Silico Transcriptomics database)." (PMID 22125638, 2011). "In pancreatic cancer, differential hydroxymethylation of genes related to pancreas development or function (GATA4, GATA6, PROX1, ONECUT1, MEIS2), and cancer pathogenesis (YAP1, TEAD1, PROX1, IGF1) have also been shown to reliably identify pancreatic cancer from peripheral blood samples." (PMID 36835649, 2023).
pancreatic ductal adenocarcinoma (2 papers, 2024 to 2025). An infiltrating adenocarcinoma that arises from the epithelial cells of the pancreas. "Interestingly, lack of METTL14 leading to increased expression of duct markers such as KRT19, SOX9, MEIS2 could have implications for pancreatic ductal carcinoma which is among the most lethal cancers in humans." (PMID 39322760, 2024).
adenoma (1 paper, 2021). A neoplasm arising from the epithelium. "MEIS2 became activated during adenoma-carcinoma transition, which is consistent with its migration promoting role in CRC and its role as a negative outcome predictor." (PMID 34094897, 2021).
Age-related cataract (1 paper, 2020). A type of cataract (opacification of the lens) that forms during the course of aging. "Third, miR-204 downregulation in age-related cataract and PCO suggest that miR-204 targets genes involved in EMT (e.g., αSMA) and oxidative stress (e.g., ALDH1A3), whereas miR-204 downregulation in congenital cataract implicated targeting of Meis2." (PMID 32070426, 2020).